NQO1 (NAD(P)H quinone dehydrogenase 1)
Diseases named in the same sentence as NQO1 in open-access papers (continued):
Sharing a sentence is not in itself a finding about the gene and the disease.
cancer (continued). "However, cancer cells were expected to react more sensitive due to their faster metabolism that can also induce higher base levels of ROS and a higher dependence on NQO1 to counteract oxidative stress, respectively." (PMID 40900796, 2025). "Additionally, Jiang and Kima also developed several TP probes to distinguish between cancer cells and normal cells based on their NQO1 expression levels." (PMID 39120303, 2024). "NRF2 is often hyperactivated in MDR cancers, leading to increased expression of antioxidants such as heme oxygenase 1 (HO-1) and NAD(P)H quinone dehydrogenase 1 (NQO1), transporter proteins like multidrug resistance protein 1/2 (MRP1/2), and detoxifying enzymes like glutathione S-transferase (GST)." (PMID 39519053, 2024). "This may be attributed to the differences in the presence of cytoprotective enzymes as HO-1 and NQO1, responsible for the cellular detoxification of highly reactive molecules between normal and cancer cells." (PMID 38398737, 2024). "Thus, the cancer cells A549 and HeLa were killed selectively because of higher NQO1 expression and increased biotin binding to the cell surface." (PMID 39120303, 2024). "Distinct mechanisms are involved in NQO1-mediated chemoresistance in cancer." (PMID 39094401, 2024). "However, once inside cancer cells with elevated levels of NQO1, the masked quinone group was reduced by NQO1, leading to self-immolating cleavage and release of the active HaloPROTAC." (PMID 38773495, 2024). "Furthermore, a cancer-targeting and NQO1-triggered theranostic prodrug containing SN-38 was developed by Kim and colleagues for a more effective cancer treatment." (PMID 39144632, 2024). "In addition, as a scavenger of superoxide anion radicals, NQO1 triggers drug resistance in cancer cells by mitigating intracellular ROS." (PMID 39094401, 2024). "Another approach was to synthesize prodrugs that could be activated by NQO1 and the cytotoxic moieties released preferentially in cancer cells." (PMID 39120303, 2024). "HIF-1α target genes such as GLUT1 and VEGF are significantly elevated in high NQO1 expressing, indicating that HIF-1α transcriptional signaling may be activated in NQO1-positive cancers and confer a poor prognosis." (PMID 39120303, 2024). "This nanoprobe was effective in distinguishing NQO1 activity levels in cancer cell lines." (PMID 39120303, 2024). "The scRNA-seq analysis revealed a potential relationship between the NQO1 mRNA expression levels and the infiltration of immune cells and stromal cells, and inhibition of NQO1 might be a promising strategy for cancer immunotherapy." (PMID 38966635, 2024). "Additionally, it is possible to take advantage of the activity of specific enzymes, including NAD(P)H:quinone oxidoreductase-1 (NQO1), that are present in particular cancer microenvironments." (PMID 36986837, 2023). "To further ascertain the precise role of NQO1 in cancer cell cycle progression, we conducted a cell cycle analysis using cancer cells that were synchronized at the G1/S phase boundary via double-thymidine blocking and subsequently released to allow progression through the cell cycle." (PMID 36793872, 2023). "However, this correlation differs in specific tumors or specific cell subtypes, suggesting that the expression and regulatory patterns of NQO1 levels vary in different cancer types and immune cell subtypes." (PMID 37583897, 2023). "In addition to NQO1 overexpression, other contributing factors drive tumor development; for example, cancer stem cells (CSCs), also known as tumor-initiating cells (TICs), initially described by Bonnet and Dick (1997)." (PMID 36980879, 2023).
cancer (continued). "In addition, in cancer cells overexpressing Nicotinamide adenine dinucleotide (phosphate): quinone oxidoreductase 1 (NQO1), Lap can catalyze the generation of hydrogen peroxide (H2O2) through futile redox cycles." (PMID 37200848, 2023). "In this study, we illustrate that a novel NQO1 bioactivatable drug, IP-DNQ, effectively eradicates NQO1-positive cancer cells by inducing both apoptosis and programmed necrosis, displaying remarkable antitumor potential compared with previously tested NQO1 bioactivatable drugs." (PMID 38136388, 2023). "To establish whether NQO1 regulates AP-1-mediated CKS1 expression in cancer cells, we analyzed the CKS1B promoter, which contains two AP-1-like elements, using a promoter deletion assay and a reporter plasmid." (PMID 36793872, 2023). "Targeting NQO1 and related pathways could offer novel strategies for therapeutic interventions in cancer treatment, exploiting the dependency of cancer cells on redox adaptation." (PMID 38264080, 2023). "In addition, publicly available data sets and immunohistochemistry were used to investigate the correlation between NQO1 expression levels and clinicopathological features in cancer patients." (PMID 36793872, 2023). "Moreover, SNPs in the UTR regions can favor the expression of NQO1 mRNA, making cancer cells resistant to chemotherapeutics agents (especially to the platinum-derived ones)." (PMID 37175546, 2023). "In view of these results, we hypothesized that NQO1 exerts regulatory effects on cell cycle progression at the G2/M phase in cancer cells." (PMID 36793872, 2023). "It was found that NQO1 facilitated the depolymerization of QPA-locked PCL by a cascade two-step cyclization process, which ultimately caused the separation of micellar structure and prompted the release of loaded medicines at the target cancer cells." (PMID 36986837, 2023). "Therefore we further explored the NQO1 correlation with immune cell infiltration in pan-cancer and immune cell infiltration by analyzing the TIMER, EPIC, and MCP counter." (PMID 37583897, 2023). "This suggests that the expression level of NQO1 mRNA in the microenvironment of specific types of cancer cells may vary according to the cancer origin, histological subtype, pathological stage, and mutation status." (PMID 37583897, 2023). "Notably, several other NRF2 target genes, such as HMOX1 and NQO1, which are associated with antioxidant activity and ferroptosis, were also downregulated in UTP11-deficient cancer cells." (PMID 37087976, 2023). "Therefore further research is required to evaluate the impact of NQO1 in specific genetic gender factors in the treatment of cancer patients." (PMID 37583897, 2023). "Our finding that NQO1 regulates CKS1B mRNA transcription supports the theory that NQO1 is a critical component of CKS1-mediated cell cycle progression at the G2/M phase in cancer cells." (PMID 36793872, 2023). "Finally, we performed immunohistochemistry to assess NQO1 expression in breast cancer tissue from progressive cancer stages." (PMID 37169843, 2023). "Developing immunotherapies that inhibit the NQO1-dependent signaling pathways may provide a promising approach to cancer treatment." (PMID 37583897, 2023). "The inhibition of the NQO1-dependent signaling pathways may provide a promising strategy for developing new cancer-targeted therapies." (PMID 37583897, 2023). "There is an abundance of synthetic and anti-cancer studies on quinoline-5,8-diones, with most stimulated by the broad range of cytotoxicity against solid tumours displayed by streptonigrin, a recognised substrate for NQO1." (PMID 37446864, 2023). "NQO1-responsive prodrugs and nanocarriers have been developed for cancer treatment." (PMID 37695786, 2023). "In view of the finding that CKS1B is upregulated by NQO1 in cancer cells, we hypothesized that NQO1 promotes CKS1B expression in cancer cells through regulation of a transcription factor." (PMID 36793872, 2023).
cancer (continued). "The antitumor efficacy of β-lapachone has been demonstrated to be majorly associated with stimulation of NAD(P)H: quinone oxidoreductase-1 (NQO1), resulting in the prompt generation of ROS and various modulations of the pathways related to cancer progression and proliferation." (PMID 38045808, 2023). "However, the extent to which specific infiltrating cell types correlate with NQO1 expression in different cancers is inconsistent." (PMID 37583897, 2023). "In conclusion, NQO1 is a potential therapeutic target, and corresponding therapeutic agents or immunotherapies could improve cancer treatment outcomes." (PMID 37583897, 2023). "Next, we focused on the potential regulatory effect of NQO1 on CDK1 in cancer cells." (PMID 36793872, 2023). "Napabucasin is an NQO1 substrate and selectively kills NQO1 high-expression cancer cells." (PMID 37570646, 2023). "To test this, we investigated CDK1 activity in relation to expression of NQO1 in cancer cells." (PMID 36793872, 2023). "To better understand the involvement of NQO1 in cell cycle progression, we investigated gene expression in RKO/pshCont and RKO/pshNQO1 cells, demonstrating that NQO1 increased transcription of CKS1B encoding the CKS1 protein in cancer cells." (PMID 36793872, 2023). "CKS1-knockdown in NQO1-expressing cancer cells resulted in an increased proportion of cells at G2/M phase relative to transfection with siCont, whereas overexpression of CKS1 decreased the proportion of cells at G2/M phase compared to NQO1-deficient RKO/pshNQO1 and MDA-MB-231/pCont cells." (PMID 36793872, 2023). "In addition, the correlation of NQO1 levels of specific cancer with various immune cell subtypes differs." (PMID 37583897, 2023). "The characteristic target-to-background signal provided by this probe can detect and differentiate human cancer cells with different levels of NQO1 activity, including cells that experience different microenvironments due to their location in multicellular tumor mimics." (PMID 36144654, 2022). "The high level of NQO1 expression in some cancer cells, coupled with its role in defense against ROS, has led to the proposal that NQO1 inhibition may be a novel and plausible therapy for this disease." (PMID 35629169, 2022). "To overcome PARPi resistance and expand its therapeutic utility, we investigated whether a combination therapy of a sublethal dose of KP372-1 with a nontoxic dose of PARPi rucaparib would synergize and enhance lethality in NQO1 over-expressing cancers." (PMID 36203459, 2022). "NQO1 is dysregulated in many cancers and considered a target for tumor treatment and diagnosis." (PMID 35845961, 2022). "The expression of NQO1 is considered as a practical and economical way to control cancer." (PMID 35308531, 2022). "Thereby, our experimental evidence further revealing that two isoforms of Keap1 (α and β) could still inhibit the expression of Nrf2 and its target genes HO-1 and NQO-1 in cancer cells." (PMID 36142252, 2022). "NQO1 is overexpressed in most solid cancers (e.g., non-small cell lung, pancreatic, breast, and head and neck), with very low expression in normal cells/tissue, and has the potential to be a promising therapeutic target for cancer treatment." (PMID 36203459, 2022). "Previous NSCLC NQO1 studies utilized mixed subtype cohorts and performed IHC and immunofluorescence with single antibodies targets, demonstrating differences in antioxidant function and prognostic outcome, which is dependent on the cancer stage." (PMID 36359002, 2022). "Furthermore, we show that KP372-1 was ten-fold more potent to kill NQO1-positive cancer cells (IC50: 0.017 μM vs. 2 μM) compared to other NQO1 bioactivatable drugs, such as β-lapachone." (PMID 36203459, 2022). "Since the anti-leukemic effects occurred in parallel to a significant induction of NQO1 mRNA levels, NQO1 could have anti-cancer activity in this human AML model." (PMID 36362202, 2022).
cancer (continued). "We determined that the NQO1 rs1800566 polymorphism was not related to the cancer risk by calculating 95% confidence intervals and odds ratios." (PMID 36338728, 2022). "Chemotherapeutic treatment of cancers with β-lap bioactivates NQO1, yielding a highly unstable hydroquinone that auto-oxidizes in an aggressive futile cycle and generates large amounts of reactive oxygen species (ROS) that are ultimately transformed to hydrogen peroxide." (PMID 35893874, 2022). "The upregulation of NQO1 may contribute to the growth of cancer cells, especially in oxidative stress environments." (PMID 35805773, 2022). "This could result in novel anti-cancer therapies, always considering that the substantial genetic variability in NQO1 would likely result in different phenotypic responses among individuals." (PMID 35629169, 2022). "Based on this evidence, we hypothesize that inhibition of NQO1 will sensitize cancer cells to chemotherapeutic drugs." (PMID 34833955, 2021). "The overexpression of NQO1 could help to clean up redundant ROS so as to reduce the damage of cancer cells." (PMID 33841805, 2021). "From this, we can hypothesize that using these phytobioactives can affect the expression of NQO1 in cancer cells." (PMID 34833955, 2021). "In vitro assays have shown that NQO1‐expressing cancer cells are more sensitive to napabucasin." (PMID 34107166, 2021). "A means of assessing NQO1 bioactivation in vivo could empower adaptive dosing strategies that could reduce the amount of agent needed while maintaining its anti-cancer benefits." (PMID 34439319, 2021). "Prior studies reported a relationship between abnormal expression of NQO1 and cancer." (PMID 34732125, 2021). "The overexpression of NQO1 can induce cell apoptosis and promote the proliferation of cancer cells." (PMID 33841805, 2021). "However, in recent years, a large amount of evidence showed that NQO1 has a two‐sided effect in the occurrence of cancer." (PMID 33841805, 2021). "Finally, several therapies, including ionizing radiation and chemotherapy, upregulate NQO1 levels in cancer cells." (PMID 34083537, 2021). "NQO1 is recognized as an attractive target in cancer as it is frequently overexpressed in tumors compared to normal tissues and increased NQO1 levels are strongly associated with late-stage disease and worse survival." (PMID 34083537, 2021). "Thus, the expression levels of NQO1 found in cancer cells and tissues should affect their sensitivity towards merosesquiterpenes." (PMID 34209047, 2021). "Furthermore, the study was extended towards the selective phytobioactives with high specificity for cancer biology, and they are efficiently targeted to tumor tissues enhancing NQO1." (PMID 34833955, 2021). "Next, we checked whether TQ was able to increase NQO1 expression in two selected carcinoma cell lines (MDA-MB-468 and HCT-116)." (PMID 34500570, 2021). "NQO1 activity is also required for the activation of cancer prodrugs." (PMID 32825392, 2020). "Compounds that induce NQO1 expression are promising strategy for cancer chemoprevention." (PMID 31909204, 2020). "Some antitumor agents become activated by NQO1 and then attack cancer cells." (PMID 32645959, 2020). "The released Lapa could increase the O2-• levels in cancer cells by NQO1 catalysis, further converting O2-• to H2O2 by SOD-mediated cascade reaction." (PMID 32483451, 2020). "Hence, both KEAP1WT and KEAP1MUT cancer cells are capable of NQO1-dependent redox cycling of β-lapachone at comparable rates." (PMID 32007910, 2020). "Intriguingly, the role of NQO1 in cancer development seems to be twofold." (PMID 32825392, 2020). "Therefore, there is a need for two different approaches to treat cancer cells with different NQO1 levels." (PMID 32645959, 2020).
cancer (continued). "It was further found that MNNG&HPV activated the P62/KEAP1/NRF2 signaling pathway to increase the transcription of antioxidant genes HO-1 and NQO-1 by upregulating p62 expression, which enhanced the antioxidant ability of cancer cells and further promoted the occurrence and development of tumors." (PMID 33123313, 2020). "In this context, NQO1 activity can be used as a marker for predicting the effect of M/A on cancer cells, as well as for stratifying patients with potential response to M/A in adjuvant settings of cancer therapy." (PMID 33204397, 2020). "Deciphering NQO1 levels in cancer patients may be helpful to exploit the use of NQO1 targeted therapy." (PMID 31909204, 2020). "Studies have shown that NQO1 may be a target for cancer therapy, and inhibition of NQO1 may improve the efficacy of antitumor chemotherapy." (PMID 33344242, 2020). "In addition, high expression of NQO1 is closely related to the occurrence and development of cancer, tumor invasion, resistance to chemotherapy, and poor prognosis of patients." (PMID 33005608, 2020). "Over the last decades, work pioneered by Boothman's group has established β-lapachone (β-lap), a NAD(P)H:quinone oxidoreductase 1 (NQO1) bioactivatable substrate, as a promising cancer therapeutic and radiation sensitizer targeting a broad spectrum of cancers including HNSCC." (PMID 33262939, 2020). "Nonetheless, current studies are still exploring NQO1 as a direct target in cancer therapy." (PMID 32605023, 2020). "Consequently, the capacity of NQO1 to produce cytotoxic hydroquinones and alter the cellular redox state exclusively in cancer cells has emerged as an effective strategy to target cancers." (PMID 33214574, 2020). "Along with low doses of anticancer agents, approaches that use activators of Nrf2 or NQO1, such as phytochemicals, can effectively reduce cancer proliferation and metastasis without causing concomitant cytotoxic effects on normal cells." (PMID 32645959, 2020). "Exposure of cancer cells to β-lap has been reported to induce toxicity and apoptosis which involves intracellular superoxide formation and oxidative stress due to futile redox cycling by NQO1." (PMID 32789798, 2020). "Different approaches are required for cancer cells with lower NQO1 activity than normal cells." (PMID 32645959, 2020). "In contrast, the overexpression of NQO1*2 did not increase cancer cell resistance against menadione, most probably due to the strongly decreased NQO1 enzyme activity showed by this variant isoform." (PMID 31480790, 2019). "For some naphthoquinones, such as β-lapachone, selectivity may also be due to overexpression of NQO1 in cancer cells since these compounds require this enzyme to become fully reactive." (PMID 31388334, 2019). "NQO1 also has roles in cancer and some neurological diseases." (PMID 31431515, 2019). "This suggests that the interaction of Polβ with NQO1 is not regulated by the status of the Polβ complex with XRCC1 (bound to or free of XRCC1) but instead is impacted by the presence of the cancer mutation, T304I." (PMID 31287140, 2019). "However, their use for real-time detection of NQO1 in biological systems, a potentially effective approach for cancer diagnosis is limited because of their short and overlapping wavelengths of excitation and emission." (PMID 31189950, 2019). "Additionally, the reduction catalysed by NQO1 has been exploited in the design of anti-cancer prodrugs." (PMID 31431515, 2019). "NQO1 expression leads to a favorable position for the development of tumor cells by protecting them from oxidative stress and chemotherapeutic agents, resulting in cancer progression and chemoresistance, as has been described for HCC." (PMID 35582588, 2019). "Taking these points into consideration and to overcome the limitations of NQ-DCP, we developed a physiologically stable new NQO1 activatable ‘turn-on’ near-infrared fluorescent probe (NIR-ASM) for monitoring endogenous NQO1 activity and noninvasive cancer diagnosis." (PMID 31189950, 2019).